MYD88 (MYD88 innate immune signal transduction adaptor)
Diseases named in the same sentence as MYD88 in open-access papers (continued):
Sharing a sentence is not in itself a finding about the gene and the disease.
myeloid malignancies (5 papers, 2013 to 2024). "Our observations that alternative splicing of genes in the MyD88 dependent pathway are important candidates in oncogenesis agree with the recent description of oncogenic IRAK4 isoforms, albeit in myeloid malignancies." (PMID 34163463, 2021). "Taken together, in two different preclinical models of myeloid malignancies (APL and HR-MDS) the survival advantage induced by the pVAX14 vaccine was concomitant with increases in IFNγ producing cells, memT, leukemic precursor-specific CD3+ cells and MyD88 expression." (PMID 26378812, 2015).
non-Hodgkin lymphoma (5 papers, 2014 to 2024). Distinct from Hodgkin lymphoma both morphologically and biologically, non-Hodgkin lymphoma (NHL) is characterized by the absence of Reed-Sternberg cells, can occur at any age, and usually presents as a localized or generalized lymphadenopathy associated with fever and weight loss. "Recent data also point to an involvement of MyD88-dependent signaling in the context of non-Hodgkin lymphomas, where MYD88 gain-of-function mutations promote tumor cell growth." (PMID 31511529, 2019). "The MYD88 L265P mutation has been shown to be a gain of function driver mutation in models such as ABC non-Hodgkin lymphoma cell lines, while activated MYD88 induces NF-kappa B signaling." (PMID 26352266, 2015).
pancreatic ductal adenocarcinoma (5 papers, 2017 to 2022). An infiltrating adenocarcinoma that arises from the epithelial cells of the pancreas. "It was reported that miR-940 targeted the 3′ UTR of MyD88, being involved in the activation of NF-κB in pancreatic ductal adenocarcinoma." (PMID 29616037, 2018). "A low level of miR-940 led to an elevated expression of MyD88 and promoted pancreatic ductal adenocarcinoma cell growth." (PMID 29616037, 2018). "Besides, miR-940 can inhibit the growth of pancreatic ductal adenocarcinoma via targeting MyD88 that involved in IL-33 mediated type 1 helper T cells (Th1) differentiation (Th1 is pivotal in cellular immunity)." (PMID 28222782, 2017).
periodontal disease (5 papers, 2021 to 2025). "However, numerous recent reports suggest that MyD88-independent TLR2 pathways may also contribute to periodontal disease progression." (PMID 34255809, 2021).
primary immunodeficiency (5 papers, 2015 to 2025). "Genetic defects in bacterial sensing arising from mutations in canonical TLR signaling pathway genes such as IRAK4 and MYD88 are established causes of primary immunodeficiency." (PMID 37097753, 2023). "Indeed, a recent study investigating immunological deficiencies in 163 children with IPD reported that 26% of cases had an underlying primary immunodeficiency (PID) although only one child had an apparent TLR-NF-kB pathway defect (MyD88 deficiency)." (PMID 25886387, 2015). "P. aeruginosa infection has been reported in children with primary immunodeficiency, including Wiskott–Aldrich syndrome, cyclic neutropenia, IRAK-4/MyD-88 deficiency, centromeric region instability, facial anomalies syndrome, and XLA." (PMID 33261572, 2020).
viral myocarditis (5 papers, 2020 to 2023). Myocarditis that is caused by an infection with a viral agent. "MyD88, the adaptor protein utilised by the majority of TLRs, is likely to be involved in the regulation of CAR expression as MyD88-deficient mice exhibit reduced CAR protein expression in the context of murine viral myocarditis." (PMID 34072044, 2021). "The SARS-CoV-2 virus may lead to aberrant TLR4 downstream cellular signalling to cause cardiac injury (viral myocarditis) and lung injury, by altering the balance between MyD88-dependent and independent signalling, given the role of TLR4 in mediating abnormal inflammation and pathological fibrosis." (PMID 33505220, 2021). "In the setting of experimentally induced viral myocarditis in mice, knockout of MyD88 led to significant reduction of p56lck expression, a molecule important in T cell activation." (PMID 34072044, 2021). "Patients with viral myocarditis have a high expression of MyD88, CD3+ lymphocytes, and collagen fibers (markers of fibrosis) in myocardial tissue." (PMID 33096896, 2020). "Lupeol downregulated the mRNA and protein expressions of TLR4 with the inhibition of the downstream MyD88 and NF-κB, restraining the release of IL-1β and TNF-ɑ, in viral myocarditis mice." (PMID 34777686, 2021). "Viral myocarditis appears to be driven more by aberrant MyD88-dependent signalling rather than the alternative TRIF/TRAM pathway." (PMID 33505220, 2021).
acute pancreatitis (4 papers, 2022 to 2025). An acute inflammatory process that leads to necrosis of the pancreatic parenchyma. "In severe acute pancreatitis rats with acute lung injury, notoginsenoside R1 promotes TOLLIP expression by inhibiting miR-128-2-5p, thereby inhibiting the expression of TLR4, MyD88, and NF-κB related pathway proteins and exerting a protective effect." (PMID 39735680, 2025).
airway hyperresponsiveness (4 papers, 2011 to 2016). "Li and colleagues reported that macrophages are involved in glucocorticoid-resistant airway hyperresponsiveness (AHR) through a MyD88-dependent mechanism." (PMID 27310495, 2016). "Importantly, we demonstrate that ODE-induced airway hyperresponsiveness is MyD88-dependent in lung resident cells, whereas MyD88 action in hematopoietic cells is mainly responsible for ODE-induced TNF-α release." (PMID 26376975, 2015).
alcoholic liver diseases (4 papers, 2017 to 2025). A disorder caused by damage to the liver parenchyma due to alcohol consumption. "In summary, CA can prevent alcoholic liver disease by inhibiting the TLR4/MYD88/NF-κB pathway and regulating the gut microbiota." (PMID 41302431, 2025). "Previous studies have reported the MyD-88 independent role of TLR-4 in alcoholic liver disease." (PMID 30057922, 2018). "In alcoholic liver disease, the gut microbiota and its components, including LPS and dsDNA, activate the TLR4/MyD88–ROS pathway in the portal circulation, thereby triggering NLRP6 inflammasome-mediated pyroptosis." (PMID 36969233, 2023). "Interestingly, despite being protected from E. faecalis -exacerbated alcoholic liver disease, chimeric mice with Kupffer cells that did not express MYD88/TRIF had a significantly higher percentage of positive Enterococcus blood cultures than mice with WT or Tlr2−/− Kupffer cells." (PMID 29038503, 2017).
atopic dermatitis (4 papers, 2016 to 2025). "For example, MyD88-deficient keratinocytes impair Langerhans cell emigration from the skin in a model of atopic dermatitis, suggesting that MC-mediated signaling downstream of MyD88 may permit efficient migration of dermal-resident DCs to draining lymph nodes due to keratinocyte-derived factors." (PMID 27741278, 2016).
celiac disease (4 papers, 2018 to 2022). An autoimmune genetic disorder with an unknown pattern of inheritance that primarily affects the digestive tract. "The downregulation was related to Myd88 and NF-kB pathway activation, constitutively active in celiac disease patients." (PMID 33572313, 2021). "In celiac disease biopsies TRAF2, STAT1, IL1RA, and MYD88 were found upregulated, and after Lnc13 upregulation, their expression was reduced, while Lnc13 knockdown was reverting the phenotype." (PMID 33572313, 2021). "Furthermore, TLRs overexpression has been associated to celiac disease, and accordingly to this observation, the stimulation of PBMCs from celiac patients with pepsin digest of wheat gliadin fraction led to IL-1β secretion via TLR4/MyD88/TRIF/MAPK/NF-kB signaling pathway." (PMID 29795662, 2018).
Chlamydia infection (4 papers, 2012 to 2017). "The signaling molecule MyD88 has been shown to play a central role for pathogen recognition, immune reaction and survival of infected individuals during Chlamydia infection in several in vivo studies." (PMID 27917158, 2016). "It is also known that some microbes induce Th17 using TLR signals; for example, Th17 cells induced by Chlamydia infection are reduced in Myd88 KO mice." (PMID 23272135, 2012). "Similarly, recent data show that MyD88 expression in CD4 T cells is important for the resolution of Chlamydia infection from the genital tract independently of TLR or IL-1R." (PMID 28817719, 2017). "Further support for this hypothesis stems from published microarray databases, where upregulation of MCL and Mincle during pulmonary Chlamydia infection was shown to be MyD88-dependent." (PMID 27005451, 2016).
CNS DLBCL (4 papers, 2019 to 2024). "CNS DLBCLs frequently harbored MYD88, CD79B and/or PIM1 mutations." (PMID 35223507, 2022). "In this study, all 3 primary CNS A-DLBCL patients displayed mutations in MYD88 L265P, which is consistent with the high frequency of MYD88 alterations reported in the literature for primary CNS DLBCL." (PMID 31109360, 2019).
colorectal tumors (4 papers, 2009 to 2025). "Il10−/− mice developed an average of 0.8 colorectal tumors/mouse while Il10−/−; Myd88−/− mice were devoid of neoplastic lesions." (PMID 19551144, 2009). "Furthermore, disruption of MyD88 signaling, a key integrator of multiple TLRs prevented the development of colorectal tumors in Il10−/− mice." (PMID 19551144, 2009). "Additionally, AOM-treated Il10−/−; Myd88−/− mice failed to develop colorectal tumors, indicating that bacterial signaling through the TLR/MyD88 system is required for development of CAC." (PMID 19551144, 2009).
cyst (4 papers, 2010 to 2025). A sac-like closed membranous structure that may be empty or contain fluid or amorphous material. "In detail, there was no significant induction of Tlr-7/MyD88-mediated pathogenic response in transgenic cyst fed group as compared to the control group challenged with S. iniae." (PMID 31824449, 2019). "Conversely, V. vulnificus induced Tlr-5/MyD88/Traf-6-mediated immune response in control tilapia fry while enhanced immunity via increased Tlr-2 and Tlr-5-mediated immune response was observed in response to V. vulnificus infection in transgenic cyst fed group." (PMID 31824449, 2019).
dementia (4 papers, 2022 to 2025). Loss of intellectual abilities interfering with an individual's social and occupational functions. "Additionally, MYD88 levels were found increased also in the hippocampus of Balb/c mice where AD-like dementia was induced through the administration of Aβ1-42 oligomers." (PMID 35277123, 2022). "Supplementation with probiotics therefore has the potential to prevent the disease and delay dementia, as it can modulate the gut-brain axis by reducing NLRP3, TLR4 and MYD88 inflammatory pathways triggered by the overgrowth of pathogenic bacteria." (PMID 40376196, 2025). "IL-1β activates the TLR2/MyD88/NF-κB pathway in Parkinson’s disease, leading to α-synuclein spreading in Parkinson’s disease (PD), multiple-system atrophy (MSA), and dementia with Lewy bodies." (PMID 40801649, 2025). "Artemisinin B improved learning and memory impairment in AD mice with dementia by suppressing neuroinflammation by reducing the gene expression levels of MyD88 and NF-κB as well as by reducing the protein levels of TLR4 and MyD88." (PMID 35746960, 2022).
diabetic kidney disease (4 papers, 2020 to 2024). Progressive kidney disorder caused by vascular damage to the glomerular capillaries, in patients with diabetes mellitus. "DMDD alleviates diabetic nephropathy by mitigating kidney damage and inflammation via the inhibition of the TLR4/MyD88/NF-κB signaling pathway." (PMID 34975464, 2021). "AOE can effectively protect kidney tissues of diabetic nephropathy, and probably through regulating level of TGF-β1/MyD88." (PMID 32660472, 2020). "Additionally, pharmacological inhibition of MyD88 by LM8 suppressed inflammation in TECs and prevented diabetic kidney disease in experimental mice probably through the NF-κB/NLRP3 pyroptosis pathway." (PMID 39000237, 2024).
esophageal cancer (4 papers, 2014 to 2024). A primary or metastatic malignant neoplasm involving the esophagus. "This indicates that the TLR4/Myd88/NF-κB signaling pathway is involved in esophageal cancer disease progression and is closely associated with LPS." (PMID 38834834, 2024). "Our results revealed for the first time that MYD88 variants are upregulated in esophageal cancer tissues compared with normal tissues." (PMID 24527027, 2014). "The results demonstrated a significant shift in the pattern of expression of MYD88 variants 1 and 3 in the esophageal cancer tissues compared with the normal tissues." (PMID 24527027, 2014). "The upregulation of FOXO3, GAPDH, and MYD88 variants in esophageal cancer suggests a role for autophagy and provides new insight into the biology of esophageal cancer." (PMID 24527027, 2014). "This indicates that EMT progression in mouse esophageal cancer may be associated with the TLR4/Myd88/NF-κB signaling pathway." (PMID 38834834, 2024). "Because this is the first report of the overexpression of the FOXO3, GAPDH, and MYD88 genes in esophageal cancer cells, the precise role of these genes in esophageal cancer remains to be elucidated." (PMID 24527027, 2014). "We propose that FOXO3, GAPDH, and MYD88 are novel targets for combating autophagy in esophageal cancer." (PMID 24527027, 2014). "The results of this study indicate significantly increased protein expression of key nodes of the TLR4/Myd88/NF-κB pathway in the esophagus of mice modeled for esophageal cancer in situ, and the same changes in protein expression were observed in esophageal cancer cells after LPS treatment in vitro." (PMID 38834834, 2024). "Mechanically, CEH activated TLR4 and MYD88 innate immune signaling, which is advantageous for the activation of the host's innate immunity to exert a balanced intestinal environment as well as to trigger a better chemotherapeutic response to esophageal cancer." (PMID 31293986, 2019). "Mechanically, CEH activated TLR4 and MYD88 innate immune signaling, which is advantageous for the activation of the host's innate immunity, for a balanced intestinal environment as well as to exert a chemotherapeutic response to esophageal cancer." (PMID 31293986, 2019). "Our findings indicated that MYD88 overexpression could lead to autophagy in esophageal cancer." (PMID 24527027, 2014). "The cause of MYD88 overexpression in esophageal cancer tissues likely originates from the extracellular tumor matrix, where the presence of mucin could trigger prolonged activation of TLR receptors and subsequent upregulation of MYD88." (PMID 24527027, 2014). "This research highlighted that ERK, JNK, and p38 MAPK activation was regulated by TLR4 pathway, and that inhibition of TLR4, MyD88, ERK, JNK, and p38 attenuated proliferation and induced apoptosis esophageal cancer cells in vitro." (PMID 27323819, 2016). "In conclusion, using the SSH method, our study revealed for the first time that the FOXO3, MYD88, and GAPDH genes are overexpressed in esophageal cancer." (PMID 24527027, 2014). "In this study, suppression subtractive hybridization was used to identify the overexpressed genes, FOXO3, MYD88, and GAPDH, which have potential roles in the induction of autophagy in esophageal cancer cells." (PMID 24527027, 2014). "Considering the fundamental role of autophagy in tumorigenesis and the high expression levels of FOXO3, MYD88 and GAPDH in esophageal cancer, further studies are needed to evaluate the roles of these genes and autophagy in the development of esophageal cancer." (PMID 24527027, 2014). "Because of intraepithelial neoplasia importance in tumorigenesis of esophageal cancer, occurrence of autophagy and expression of FOXO3, MYD88, and GAPDH genes should be studied in this stage." (PMID 24527027, 2014).
esophageal cancer (continued). "Additionally, in vitro experiments revealed that LPS from Bacteroides fragile promoted esophageal cancer cell proliferation, migration, and invasion, and induced EMT by activating the TLR4/Myd88/NF-κB pathway." (PMID 38834834, 2024). "The overexpression of the FOXO3, MYD88, and GAPDH genes could lead to the induction of autophagy genes in esophageal cancer." (PMID 24527027, 2014).
gestational diabetes mellitus (4 papers, 2016 to 2025). "SIN has therapeutic effects in streptozotocin-induced gestational diabetes mellitus (GDM) rats with high safety, which is associated with the inhibition of inflammation and oxidative stress via the TLR4/MyD88/NF-κB signaling pathway." (PMID 41200108, 2025).
herpesvirus infections (4 papers, 2015 to 2019). "In summary, our study shows that MyD88 responses are dispensable for the induction of protective IFN-I responses against a systemic herpesvirus infection in mice." (PMID 25954804, 2015). "Nevertheless, MyD88 deficient patients do not have an increased susceptibility to herpesvirus infections, implying redundancy of different PRR sensing mechanisms." (PMID 31249303, 2019). "Interestingly, MyD88 deficient patients do not show enhanced susceptibility to herpesvirus infections, but under such conditions a functional cGAS/STING axis might be essential to compensate for the loss of TLR signaling." (PMID 31249303, 2019). "Because individuals devoid of MyD88 function do not suffer from enhanced incidence or severity of herpesvirus infections, it is likely that in the pathogenesis of HCMV infected humans pDC-derived IFN-I do not play a critical role." (PMID 27058035, 2016).
intestinal tumors (4 papers, 2010 to 2023). "MyD88−/− mice show no proliferation in IECs after AOM-DSS treatment, however, MyD88−/− mice show an overall increased susceptibility to AOM-DSS induced intestinal tumors due to an upregulation of Wnt signaling associated genes, angiogenesis and DNA repair." (PMID 37519301, 2023). "In the absence of a chronic inflammation, MyD88 deficiency has been shown to result in resistance to intestinal tumor development in the ApcMin/+ and AOM mouse models, demonstrating that MyD88 signaling can have both tumorigenic and anti-tumorigenic effects depending on the inflammatory context." (PMID 37519301, 2023). "Previous studies have shown that TLR signaling and the common adaptor molecule MyD88 are critically involved in intestinal epithelial cell homeostasis and the development of intestinal tumors, yet the role of TLR2 has not been extensively studied." (PMID 20885960, 2010).
intracerebral hemorrhage (4 papers, 2012 to 2022). A cerebrovascular disorder characterized by bleeding into one or both cerebral hemispheres including the basal ganglia and the cerebral cortex. "In conclusion, our findings reveal that heme triggers TLR4-mediated inflammatory injury via the MyD88/TRIF signaling pathway in intracerebral hemorrhage in mouse brain." (PMID 22394415, 2012). "Additionally, in a mouse model of intracerebral hemorrhage, Heme interacts with TLR4 receptor, activates TLR4-mediated inflammatory injury through the MyD88/TRIF signaling pathways." (PMID 23967200, 2013).
lung disease (4 papers, 2012 to 2025). "Current studies suggest that MyD88 may be important in resolution processes of environmentally triggered lung disease." (PMID 32321514, 2020). "Inflammasome-dependent contributions of monocytes and macrophages to human COPD have not been fully elucidated, but are strongly suggested by animal models of smoke-induced and elastase-induced lung disease which display both IL-1R/MyD88 dependence and strong macrophage contributions." (PMID 23226468, 2012).
lymphoproliferative disorders (4 papers, 2024). "Although type II cryoglobulinemia can also be caused by lymphoproliferative disorders, only two reported cases have suggested that BTK inhibitors were effective in type II cryoglobulinemia, both of which involved patients with a mutation in the MyD88 gene." (PMID 38765016, 2024).
memory impairment (4 papers, 2011 to 2025). "In studying diseases such as memory impairment and neurological damage after cerebral ischaemia‐reperfusion, animal models of cerebral ischaemic stroke reflect that the TLR4/MyD88/NF‐kB axis is involved in neuroinflammation." (PMID 35393774, 2022).